KRAS (KRas proto-oncogene, GTPase)
Diseases named in the same sentence as KRAS in open-access papers (continued):
Sharing a sentence is not in itself a finding about the gene and the disease.
tumor (continued). "The activation or upregulation of NF-κB via multiple routes, including but not limited to the TME, tumor-associated macrophages, or oncogenic mutations in KRAS, has been shown to favor cancer tumorigenesis, angiogenesis, and metastasis." (PMID 39941724, 2025). "Higher genetic heterogeneity has been reported in early-stage disease, with selective survival of tumor cells containing key driver mutations (such as KRAS, EGFR variants, etc.)that impart enhanced invasive potentials." (PMID 40282516, 2025). "Patients with high tumor invasion depth (T3/4), driver gene mutation, and KRAS mutation had a higher MICA-129 Met/Met genotype." (PMID 41431073, 2025). "Tumor grade followed a similar trend, with G3 tumors having a significantly higher prevalence of KRAS (p=0.01) and BRAF (p=0.0003) mutations." (PMID 40949797, 2025). "Oncogenic mutations, notably in the KRAS gene, dictate drug sensitivity and drive tumor initiation and progression." (PMID 39774001, 2025). "We next investigated the anti-tumor efficacy of adagrasib and abemaciclib in intracranial tumor models carrying KRAS-G12C and CDKN2A loss." (PMID 40317086, 2025). "The tumor was staged as pT4N0M0, with Kirsten rat sarcoma viral oncogene homolog (KRAS) mutations positive." (PMID 41161734, 2025). "Due to advances in genetic research, it is now classified as a true tumor, associated with mutations in the KRAS gene." (PMID 39941213, 2025). "Firstly, KRAS mutation profiling aids in diagnosis and tumor classification, given the association of specific mutations with distinct cancer types." (PMID 41514544, 2025). "STK11 mutations often co-occur with activating KRAS mutations and are associated with aggressive tumor behavior, immunosuppressed phenotypes, and reduced response to therapy." (PMID 40725389, 2025). "The mutational status of primary tumours has also been related to the site of metastasis, with primary tumours harbouring KRAS mutations more commonly metastasising to the lung compared to the liver." (PMID 41226343, 2025). "A hallmark of PC is oncogene-driven metabolic reprogramming—notably mediated by mutations in KRAS and other key pathways—which fuels tumor progression and undermines the efficacy of neoadjuvant treatments." (PMID 40508051, 2025). "Alterations in KRAS mutation-specific allelic imbalance can enhance tumor aggressiveness by promoting invasion and metastatic capabilities." (PMID 40595916, 2025). "In vitro studies have shown its efficacy on various forms of RAS, and in animal models, tumor regression with various KRAS mutations (G12D, G12V, G12C) was dose-dependent." (PMID 40805153, 2025). "This association suggests a potential link between tumor purity and the detection of KRAS mutations." (PMID 40981070, 2025). "For this reason, patients with advanced CRC should undergo genetic tumor analysis to detect KRAS/NRAS and BRAF mutations, HER2 amplifications, and microsatellite instability (MSI)/mismatch repair (MMR) status, among other biomarkers." (PMID 40507337, 2025). "In the present study, KRAS mutations were identified in 88% of the tumor tissues from the 41 PDAC patients." (PMID 40596921, 2025). "On the other hand, KRAS mutations often indicate aggressive tumor behavior, necessitating more extensive resections to minimize recurrence risk." (PMID 39796742, 2025). "In this study, SBT/carcinoma pairs showed concordant profiles in 56% of KRAS-mutated tumor cases, 31% of wild-type tumor cases, and only 13% of BRAF-mutated tumor cases." (PMID 40564801, 2025).
tumor (continued). "We look forward to improving the co-mutation-based tumor typing paradigm for KRAS mutations in the future, intending to guide clinical immunotherapy." (PMID 40611261, 2025). "Nearly 90% of PDAC cases harbor KRAS mutations, which activate downstream pathways that support tumor growth, migration, and metabolic adaptation." (PMID 40722937, 2025). "Somatic mutations in oncogenes, such as KRAS, significantly modify tumor metabolic processes, which are key factors in inducing tumor progression and immune escape." (PMID 41184283, 2025). "Stratification by tumor subtype revealed KRAS mutations in 24.9% (n = 554/2227) of patients with IHC, 32.2% (n = 513/1593) of those with EHC, and 9.4% (n = 131/1388) of those with GB." (PMID 40499463, 2025). "KRAS mutations promoted metabolic reprogramming, increasing tumor dependency on glutamine, lactate, and ammonia." (PMID 40485603, 2025). "The KRAS protein can be both membranous and cytoplasmatic, where cytoplasmatic KRAS protein has been associated with resistance towards tumor promoting KRAS mutations." (PMID 40596921, 2025). "Biomarkers to guide the selection of the most appropriate therapy include tumor histology, such as KRAS/BRAF mutations, HER2 amplification, and microsatellite instability-high (MSI-H)." (PMID 40547026, 2025). "Under the assumption of clonal tumor expansion, the same KRAS mutation would be present in all tumor cells." (PMID 40596921, 2025). "Together, these results indicate that BMS309403 efficiently inhibited tumor growth and overcame cetuximab insensitivity in KRAS-mutated cells by targeting the degradation of the KRAS protein." (PMID 39823981, 2025). "The metabolic reprogramming associated with KRAS mutations is accompanied by a reshaped proteomic landscape that promotes aggressive tumor behavior." (PMID 41294676, 2025). "The analysis of TB showed that there was an association between the presence of KRAS mutation and an increased number of tumour buds, with 36 cases (66.7%) containing between 7–12 tumour buds." (PMID 39996841, 2025). "KRAS mutations shape the immune microenvironment, affecting tumor progression and treatment efficacy." (PMID 40611261, 2025). "KRAS mutation was associated with low-grade tumours in 50 of the mutated cases (92.6%), while the other four cases were diagnosed as high-grade tumours (7.4%)." (PMID 39996841, 2025). "The KRAS G12 mutation detection rate was similar across the sequencing technologies in the samples with high tumor purity ( > 50th percentile) (RNA-seq, 78.1%; WES, 79.2%; TS, 83.3%)." (PMID 39779977, 2025). "The selected panel of PDAC cell lines reflects the patient tumor landscape, with seven out of eight lines harboring KRAS mutations, while BxPC-3 is the only RAS wild-type cell line." (PMID 40722937, 2025). "With KRAS mutations and other oncogenic alterations shaping stress responses, future research should focus on identifying biomarkers that predict tumor dependencies." (PMID 40527836, 2025). "For example, KRAS mutations are used to guide treatment with Sotorasib, while tumor expression of (wild type) human epidermal growth factor receptor 2 and 3 (HER2 and HER3) are used to select patients for trastuzumab and cetuximab, respectively." (PMID 41727309, 2025). "These approaches rely on either known mutations from sequencing the patient-matched tumor or mutations prevalent in the tumor type, such as those at positions of hotspot alterations in KRAS." (PMID 40397745, 2025).
tumor (continued). "SiRNA-based therapies have emerged as a promising cancer treatment strategy, targeting KRAS mutations to silence mutant KRAS mRNA, preventing its translation and inhibiting tumor progression." (PMID 40805153, 2025). "Analysis of the TEMPUS molecular profiling demonstrated the presence of a KRAS gene mutation in our tumor sample, which is considered a key molecular feature of PRNRP." (PMID 40989704, 2025). "In tumor tissue, mutations in genes like KRAS, BRAF, and MYC impact polyamine metabolism, leading to an increase in polyamine content within the tissue." (PMID 40390766, 2025). "In contrast, MACCS2 was enriched in tumor-suppressive and immune-associated pathways such as KRAS signaling, interferon-γ response, and angiogenesis, underscoring the functional divergence between the two subtypes." (PMID 41037214, 2025). "LKB1 mutant/KRAS mutant NSCLCs showed significantly decreased tumor-associated macrophages, tumor-infiltrating lymphocytes, and PD-L1 expression and increased tumor-associated neutrophils compared to KRAS mutant only tumors." (PMID 40255421, 2025). "Subtype 5, called 'immunogenic', showed frequent tumour-infiltrating lymphocytes (TILs)-associated patterns, enrichment in KRAS mutations and in immune-related pathways such as TNFα signalling via NF-kB." (PMID 40849356, 2025). "HIF-1α, a critical regulator of cellular responses to hypoxia, is often overexpressed in cancer due to genetic alterations such as gain-of-function mutations in oncogenes such as the KRAS mutation and loss-of-function mutations in tumor suppressor genes." (PMID 39996842, 2025). "The evidence presented supports a pivotal function for signaling associated with the KRAS pathway and macrophage infiltration in shaping tumor progression, immune evasion, and therapeutic responsiveness." (PMID 40607411, 2025). "Nuclear S102 YB-1 was expressed in 47.2% of tumor tissues, which was positively correlated with KRAS mutation (P = 0.017)." (PMID 40420381, 2025). "Tumor-intrinsic EphA2 has been shown to have both tumor-promoting and tumor-suppressing effects in the presence of KRAS mutations." (PMID 40867322, 2025). "Alterations at any of these three tumor suppressors identified approximately 50% of the patients with KRAS‐mutated NSCLC who experienced disease progression within 3 months from initiation of therapy." (PMID 41387924, 2025). "This is notable because KRAS G12C inhibitors such as sotorasib and adagrasib have recently been approved as tumor-agnostic therapies for cancers harboring this mutation." (PMID 41154355, 2025). "It selectively binds to the Cys12 residue of the mutated KRAS protein and, as a result, can inhibit tumor growth, KRAS activation and downstream signaling at nanomolar concentrations." (PMID 40597785, 2025). "Conversely, KRAS mutations elevate ROS levels, thereby intensifying DNA damage stress and compelling tumor cells to rely more heavily on residual HR mechanisms for survival." (PMID 40510156, 2025). "These agents included the XPO1 inhibitor, eltanexor, and the KRAS G12D specific inhibitor MRTX-1133 which had activity in tumor lines harboring the KRAS G12D mutation." (PMID 40470182, 2025). "Analysis of non-KRAS genetic aberrations in ctDNA additionally inform microsatellite instability and tumor mutational burden, which clinically inform susceptibility of disease to immunotherapeutic agents." (PMID 40182037, 2025). "Point mutations in KRAS can lock the protein in a constitutively active state, resulting in uncontrolled proliferation and tumor progression." (PMID 40723238, 2025). "The most common KRAS oncogene mutations occur in codons 12, 13, and 61 and their presence has been well-documented to lead to increased tumor proliferation and worse overall survival." (PMID 40227779, 2025). "The KRAS oncogene has attracted notable attention because of its frequent mutation and its role in initiating and sustaining tumor growth." (PMID 40091835, 2025).
tumor (continued). "It is notable that 80% of tumor tissues collected to generate PDOs with PIK3CA mutations also harbored KRAS mutations." (PMID 39808497, 2025). "This metaplastic transformation parallels the early changes observed in human gastric carcinogenesis, where KRAS-mutated cells show enhanced mucin production and altered differentiation patterns that precede frank neoplasia." (PMID 40673273, 2025). "Another mutation that occurs alongside KRAS in PDAC is the ERBB2 mutation, which enhances KRAS-driven traits and fosters tumor growth." (PMID 40805153, 2025). "KRAS mutations were present in tumor tissues from 12 (46%) stage I, 27 (73%) stage II, and 24 (53%) stage III cases in the study cohort." (PMID 40282516, 2025). "The KRAS-mutant tumors exhibit mutation-specific TMEs, primarily accounting for the heterogeneity of anti-tumor responses of immunotherapy in KRAS-mutant tumors." (PMID 41184283, 2025). "KRAS mutations, particularly the KRAS-G12D substitution, have been shown to impair the tumor immune microenvironment (TIME) by reducing PD-L1 expression and chemokine secretion, which limits CD8+ T cell recruitment and promotes immunosuppression." (PMID 40739089, 2025). "Continued research into how KRAS mutations affect tumor biology and the metastatic process is essential for developing more effective therapeutic strategies." (PMID 40282985, 2025). "Among these, the KRAS/G12C mutation is particularly interesting due to its prevalence and impact on tumor development." (PMID 40286847, 2025). "Survival benefits were observed across PD-L1 strata, tumor histologies, and high-risk molecular subgroups such as KRAS, STK11, and KEAP1, and in patients with brain metastases." (PMID 41479494, 2025). "Although KRAS mutations are generally unrelated to LNM status or tumor characteristics, our study demonstrates a shift in KRAS mutation rates across the two LNM-negative subtypes, potentially offering survival benefits to CRC patients with BRAF mutations." (PMID 40991561, 2025). "Second, some KRAS mutations are immunogenic and can elicit endogenous anti-KRAS T cell responses, and T cells targeting tumor neoantigens appear to be the main mediators of many effective cancer immunotherapies in humans." (PMID 39846249, 2025). "We next used a subcutaneous xenograft tumor model and the two KRAS-mutated cell lines in NOD/SCID mice." (PMID 40055523, 2025). "These markers offer the potential for high specificity, as they can detect tumor-specific mutations (e.g., KRAS in ctDNA) or carry tumor-derived cargo (e.g., microRNAs in EVs)." (PMID 41463153, 2025). "Additional studies even point to genetic relationships of PD-L1 expression itself in KRAS mutations and mRNA regulation, further illustrating the interplay between inherited genetics and tumor-immune interactions." (PMID 40721801, 2025). "There was a 94.7% agreement between ctDNA and tumor tissue for KRAS and EGFR mutations, reinforcing the reliability of ctDNA for molecular profiling." (PMID 40426987, 2025). "Another study found a significant association between L1CAM expression and tumor invasion and metastasis in KRAS mutant patients." (PMID 40282985, 2025). "Here, we show how SMAD4 loss in PDAC malignant cells shapes tumor biology differently in the presence of two distinct KRAS mutations." (PMID 39841099, 2025). "In terms of tumor aggressiveness, KRAS mutations are associated with more aggressive tumor behavior and a higher risk of metastasis, especially liver lesions." (PMID 40868288, 2025).
tumor (continued). "In PDAC, tumor- and nerve-derived Sema3D reprogram macrophages indirectly via KRAS mutation-dependent adenosine diphosphate-ribosylation factor 6 (ARF6) signaling in tumor cells." (PMID 41163091, 2025). "This is explained by the strong enrichment for KRAS mutations among NS-LUAD tumours on the SD trajectory, versus the enrichment for EGFR mutations among those on the NSD trajectories." (PMID 41509216, 2025). "We demonstrate that RBCEVs loaded with ASOs efficiently inhibit mutated KRAS genes while sparing cells with the WT gene, leading to tumor cell death." (PMID 40585984, 2025). "Usually, KRAS mutations promoted neutrophil infiltration, typically associated with a pro-tumor phenotype." (PMID 40611261, 2025). "Current evidence indicates that type I IFN signaling deficiency manifests during early tumorigenesis in KRAS-mutant neoplasms and persists throughout disease progression." (PMID 40303413, 2025). "Potentially due to the smoking history, KRAS-mutant tumors typically manifest a higher tumor mutational burden (TMB) than their EGFR-mutant counterparts." (PMID 40524071, 2025). "Mutations in KRAS can lead to constitutive activation of these pathways, resulting in uncontrolled cell growth and tumor development." (PMID 40427213, 2025). "We identified a significant difference in HIF-1α expression in the tumor microenvironment between the mKRAS G12C group and other KRAS mutation groups (p = 0.017)." (PMID 39996842, 2025). "Mechanistically, mutationally activated KRAS drove the production of lactate in tumor cells, which then functioned as a substrate to increase H3K9la level." (PMID 40707783, 2025). "High-affinity TCRs for the KRAS G12V mutation have also shown improved anti-tumor activity with fewer off-target effects." (PMID 40356763, 2025). "As with NF1 mutations, KRAS mutations increase tumor-promoting immune cell function in the TME, which suggests these compounds offer a promising new therapeutic strategy for PNF and MPNST." (PMID 40563570, 2025). "Clinical proof-of-concept now demonstrates that neoantigens from driver mutations like KRAS G12D can be successfully targeted, yielding objective tumor regression." (PMID 41567982, 2025). "Of specific importance, this study is not able to address the differing pre-clinical and clinical findings that SETD2 is associated with tumor growth in KRAS-driven adenocarcinoma, while also being associated with more favorable outcomes." (PMID 41228333, 2025). "Strategies such as T-cell receptor (TCR)-engineered T-cells and tumor-infiltrating lymphocytes (TILs) are being explored to enhance the immune recognition of KRAS mutations." (PMID 40361439, 2025). "The identification of KRAS-associated regulatory T cell enrichment and chemoresistance-associated circulating tumour-initiating cells provides valuable insights for guiding immunological and pharmacological interventions." (PMID 41190015, 2025). "Well-known pathogenic mutations were only detected in the tumor tissues: p.G12D in KRAS in patients S428 and S430, and p.E545K in phosphatidylinositol-4,5-bisphosphate 3-kinase catalytic subunit alpha (PIK3CA) in patient S170." (PMID 41301905, 2025). "KRAS mutations are also frequently observed in various other cancers and play an essential role in tumor survival, driving early efforts in therapeutic development." (PMID 39941797, 2025). "The KRAS mutation dosage has greater clinical relevance than the KRAS mutation copy number and tumor cellularity, which are correlated with dosage." (PMID 39779977, 2025).